CDKN2A (cyclin dependent kinase inhibitor 2A)
Diseases named in the same sentence as CDKN2A in open-access papers (continued):
Sharing a sentence is not in itself a finding about the gene and the disease.
melanoma (continued). "In addition, melanoma patients carrying MC1R variants as well as CDKN2A mutations, show clinically hypopigmented nevi and, at RCM, roundish cells infiltrating the dermo–epidermal junction." (PMID 34356109, 2021). "Further analysis of TCGA skin cutaneous melanoma dataset revealed that the frequency of CDKN2A genetic alterations was not influenced by gender; 63/135 (47%) females and 98/228 (43%) males showed melanoma-associated CDKN2A genetic changes, and this is in keeping with a previous report." (PMID 33076392, 2020). "Modifier genes for melanoma kindreds carrying CDKN2A mutations have also been reported." (PMID 33076392, 2020). "The spectrum of tumors in relatives diagnosed with cancer in the families of six CDKN2A mutation carriers included melanoma (7×), breast cancer (3×), rectal cancer (2×), and gastric, pancreatic, lung, and endometrial cancer, brain tumor, and leukemia (one each)." (PMID 33050356, 2020). "Interestingly, CDKN2A gene mutations are found in up to 40% of familial cases of melanoma, up to 25% of head and neck squamous cell carcinomas (HNSCC), some breast cancers and pancreatic cancers, and others." (PMID 33167404, 2020). "However, few mutations were identified in the reported melanoma-susceptibility genes CDKN2A and CDK4." (PMID 32083130, 2020). "One patient had a mutation in high-risk melanoma gene, CDKN2A p.W15*." (PMID 33077847, 2020). "Notably, MC1R variants have been shown to increase the penetrance of CDKN2A mutations, doubling the risk for melanoma." (PMID 32429485, 2020). "Furthermore, in a Swedish study, familial melanoma cases with the CDKN2A mutation were associated with a younger age at onset and worse survival than those without the mutation." (PMID 32429485, 2020). "It is known that life-time risk (penetrance) of melanoma in carriers of CDKN2A mutations may be modified by other genetic and environmental factors." (PMID 32760473, 2020). "Finally, a CDKN2A germline deletion of the p14ARF-specific exon 1ß was associated with excess risk for melanoma, astrocytoma, neurofibromas, and schwannomas." (PMID 33076392, 2020). "The predominant high-risk familial melanoma genes are CDKN2A and CDK43–5." (PMID 33077847, 2020). "However, the literature indicates that CDKN2A, one of the most important genes for melanoma susceptibility, also does not correlate with patient survival, despite its important association with melanoma susceptibility." (PMID 32276436, 2020). "In the present study, a cohort of patients SPMs (n = 20) and MPMs (n = 19), sex-matched, was analyzed with our custom NGS panel that included 32 genes involved in melanoma susceptibility (e.g., CDKN2A, BAP1, POT1) and skin/hair pigmentation (e.g., TYR, TYRP1, OCA2)." (PMID 33748184, 2020). "For instance, germ-line deletions of lncRNA ANRIL, located in the CDKN2A/B or INK4-ARF locus on chromosome arm 9p21, have been associated with an increased risk of melanoma and neural system tumor development in several families in the United States and Europe." (PMID 33329688, 2020). "Regarding melanoma, while risk estimates were not reliable for most genes due to a smaller melanoma cohort size, PVs in CDKN2A were expectedly associated with very high risks for melanoma (OR = 114.6); however, PVs in ATM and BRCA1 were also elevated (two- to threefold increased risks)." (PMID 31406321, 2020). "The other three subtypes, as well as melanoma of unknown primary, were dominated by driver mutations in the genes of the cell cycle control (CDKN2A) and the RTK/RAS signaling pathway (BRAF, NRAS, ERRB2)." (PMID 32825510, 2020).
melanoma (continued). "The progressively rising probability of CDKN2A mutation prevalence with an increasing number of affected relatives with melanoma was described by Goldstein and colleagues in their study analyzing families of a European descent with at least three melanoma patients." (PMID 33050356, 2020). "Furthermore, the deregulation of pRb pathway due to CDKN2A or CDK4 gene mutations is particularly frequent in melanomas arising from skin chronically exposed to sun." (PMID 31142321, 2019). "CDKN2A, encoding cyclin-dependent kinase Inhibitor 2A, plays important roles in melanoma." (PMID 30779739, 2019). "Presence of MC1R variants, together with CDKN2A mutations, significantly increases melanoma risk." (PMID 31717496, 2019). "Mutations of CDKN2A gene account for roughly 20% of melanoma cases." (PMID 31142321, 2019). "In contrast, incidence of somatic CDKN2A mutations in sporadic melanomas is very low." (PMID 31717496, 2019). "Modifier genes for melanoma have been well described in literature for CDKN2A mutation carriers." (PMID 31203567, 2019). "The CDKN2A locus causative in human familial melanoma was studied in MeLiM pigs; however, haplotype analysis, allelic association, and linkage analysis led to exclusion of this gene from candidates for melanoma susceptibility." (PMID 31717496, 2019). "Both were diagnosed for melanoma before the age of 50 and tested wild type for CDKN2A mutations." (PMID 29523635, 2018). "CDKN2A is a tumor suppressor gene and inactivating mutations in this gene are 7-10 times more frequent in patients with a strong family history of melanoma, in comparison to those with sporadic melanoma." (PMID 29492214, 2018). "Thus, miR-204 represents a relevant mechanism in melanoma, with potential prognostic value and its loss seems to act in the CDKN2A pathway, in cooperation with NRAS." (PMID 29523154, 2018). "Although the underlying genetic basis in the majority of melanoma-prone families is unknown, certain highly penetrant genes, such as the cyclin-dependent kinase inhibitor 2A (CDKN2A) gene and cyclin-dependent kinase 4 (CDK4), have been implicated." (PMID 29774366, 2018). "A series of 32 melanoma cell lines - eight derived from surgically-excised primary melanomas, seventeen from cutaneous or lymph nodal metastases - were firstly investigated for mutations in the three main genes (BRAF, NRAS, and CDKN2A) involved in melanoma pathogenesis." (PMID 29492214, 2018). "Notably, 8–12% of melanoma is linked to mutations in CDKN2A of the chromosome 9 p21 locus, in which an alternative start codon is formed which leads to decreased levels of the functional protein." (PMID 30551605, 2018). "Familial atypical multiple mole melanoma may be caused by a mutation in CDKN2A, and in around 40% of cases the second most commonly observed malignancy in families with the CDKN2A mutation is PDAC." (PMID 29329208, 2018). "Somatic CDKN2A mutation was observed in 13% of melanoma cases in the TCGA analysis." (PMID 29464027, 2018). "One study reported that 15% of all melanoma cases in Greece have germline mutations in CDKN2A." (PMID 28973033, 2017). "Chromosomes 9 and 16 harbor the known melanoma susceptibility loci, CDKN2A and MC1R, respectively." (PMID 28973033, 2017). "In the case of melanoma, it would be pertinent to assess familial clusters, with sites which are manifested in CDKN2A and BAP1 mutation carriers, or whether the risks could be extended to as yet unknown cancer sites." (PMID 28198461, 2017).
melanoma (continued). "Only one specimen showed a variant known to predispose to melanoma p.Ala148Thr of CDKN2A." (PMID 27776349, 2017). "Norway has among the highest incidences in the world of malignant melanoma with an accumulated risk up to the age of 75 of 2.4 % for both genders, while mutations in CDKN2A and CDK4 were only found in 6.9 % in a population-based study among individuals with multiple primary melanomas (MPM)." (PMID 27804060, 2017). "Co-occurrence of pancreatic cancer and melanoma usually occurs in the setting of a CDKN2A mutation." (PMID 28283772, 2017). "Germline mutations in the CDKN2A gene are typically found in 20 to 40% of melanoma families, which may also have an increased incidence of PC." (PMID 29216274, 2017). "Only one relative showed a CDKN2A variant known as predisposing to melanoma, p.Ala148Thr." (PMID 27776349, 2017). "In addition, a third melanoma cell line-specific mutation, CDKN2A, showed an approximate 30-fold mutation enrichment in the xMD sample (83.6% vs. 2.7%)." (PMID 26999048, 2016). "The UK family with the promoter variant was identified came from a series of 139 three-or-more case melanoma families, of which 56 (40 %) have a CDKN2A mutation; 2 (1.4 %) have a CDK4 mutation, 4 (2.8 %) have shelterin mutations, and now 1 (0.7 %) has a TERT promoter mutation." (PMID 26433962, 2016). "In the general population, the prevalence of CDKN2A mutations in primary melanomas is only 1.2%; however, germ-line mutations in this locus were reported in approximately 20–57% of families with at least three cases of melanomas." (PMID 27833586, 2016). "Two high-risk genes associated with melanoma have been identified so far: CDKN2A and CDK4." (PMID 27022491, 2016). "A premature start codon by a germline mutation altering CDKN2A predisposes to melanoma." (PMID 26992833, 2016). "Germline mutations in CDKN2A are responsible for familial melanoma syndromes, such as the intensively studied p16-Leiden truncation mutation which causes familial atypical multiple mole-melanoma susceptibility." (PMID 27519597, 2016). "However, the studies showing a higher independent prevalence of mutations in the CDKN2A gene for patients with melanomas are small." (PMID 27022491, 2016). "Even though high melanoma risk alleles clearly exist in e.g. CDKN2A, it is speculated if the melanoma risk might be attributable to combinations of low to moderate risk alleles in e.g. MC1R, TYR, and ASIP." (PMID 26938746, 2016). "In our study, we detected methylation differences at MGMT body both in peripheral blood and in tumor samples: CDKN2A-mutated patients showed a low-level hypermethylation in leukocytes compared to other melanoma patients, while tumors showed hypomethylation compared to melanocytes." (PMID 26106605, 2015). "The average age of first melanoma was 42.8 years in CDKN2A mutation carriers (excluding those carrying the missense variant in p14), which is significantly younger (48.3 years, p = 0.035) than non-CDKN2A mutation carriers." (PMID 25803691, 2015). "CDKN2A/p16INK4a is the main melanoma susceptibility gene identified to date." (PMID 26498684, 2015). "Mutations in CDKN2A have been associated with 25%–40% of familial melanomas." (PMID 26393652, 2015). "CDKN2A mutation analysis can sometimes be helpful as we have published before, and is illustrated by the case above, to differentiate between a new primary and a melanoma metastasis." (PMID 25593912, 2014).
melanoma (continued). "Moreover, carriers of mutations in BRCA2 - the BC predisposition gene - have an increased risk of melanoma, while carriers of mutations in the melanoma susceptibility gene - CDKN2A - exhibit a higher than expected risk of BC." (PMID 25077705, 2014). "Germline mutations in CDKN2A are detected in 20 to 40% of melanoma families." (PMID 25893138, 2014). "Finally, we observed that the expression signatures indentified in phenotypically normal cells carrying CDKN2A mutations or MC1R variants are maintained in skin cancer tumors (melanoma and squamous cell carcinoma)." (PMID 24742402, 2014). "In addition, number of nevi and melanoma risk have been associated with variants in the CDKN2A gene, which plays a role in cell cycle regulation, while CDKN2A inactivation has been shown to be common in breast cancer." (PMID 24915306, 2014). "As reported in other founder populations with other CDKN2A mutations our findings are in concordance with the so-called divergent pathways hypotheses: familial melanomas tend to follow the nevus pathway." (PMID 25893138, 2014). "Early age at onset in the absence of a family history might only be a weak predictor of CDKN2A mutations, which notably are rare in childhood and adolescent melanoma (1.4% of cases in one study)." (PMID 25780468, 2014). "Germline mutations in CDKN2A are found in approximately 20 to 40% of melanoma families." (PMID 25893138, 2014). "Of the 62 familial melanoma patients, 17 were found to be carriers of a CDKN2A mutation." (PMID 25893138, 2014). "This confirms that the most important predictors of germline CDKN2A mutations in melanoma cases unselected for family history of the disease are the same as for those from multiple-case families: namely the presence of multiple primaries and the strength of the family history." (PMID 25780468, 2014). "One possible reason is that melanomas in individuals with CDKN2A mutations may develop from telomere-independent mechanisms." (PMID 23990928, 2013). "This represents a unique study that investigated a large homogenous case–control population for the association of tagging polymorphisms on chromosome 9p21 discovered through genome wide association studies and polymorphisms at the CDKN2A locus with melanoma risk and association with host factors." (PMID 23816148, 2013). "However, despite the contribution of CDKN2A mutations for oncogenesis, the absolute risk of melanoma in mutation carriers is still highly shaped by environmental and pedigree factors." (PMID 23634303, 2013). "In addition statistically significant association with melanoma risk was also observed for the variant T-allele of the polymorphism rs2811710 located in intron 1 of CDKN2A/ARF (OR 1.15, 95% CI 1.00-1.32)." (PMID 23816148, 2013). "In addition for the variants selected for tagging CDKN2A gene; the strongest association with melanoma risk was observed for rs3088440 (3′UTR of CDKN2A gene) that has been inconsistently associated with melanoma in previous studies." (PMID 23816148, 2013). "In addition we also genotyped 15 variants tagging the CDKN2A gene and we observed a statistically significant association with melanoma risk for the previously inconsistently associated rs3088440 variant." (PMID 23816148, 2013). "Moreover, the presence of an MC1R variant in addition to a CDKN2A mutation significantly increases the melanoma penetrance, decreasing the age at onset compared with individuals carrying a CDKN2A mutation alone." (PMID 24416617, 2013). "Down-expression of another cancer susceptibility gene, CDKN2A (predisposing to melanoma, cancers of the pancreas, breast and lung), led to speculation that the gene may have a role in the pathogenesis of psoriasis." (PMID 23805825, 2013). "CDKN2A mutations occur in approximately 20-40% of melanoma-prone families world-wide." (PMID 23371019, 2013).
melanoma (continued). "A combination of three polymorphism of CDKN2A spanning the coding exon 1a (rs2811710), the first intron (rs2518720), and the 5′ regulatory region (rs2811708) was also reported significantly associated with decreased OS in melanoma." (PMID 22911710, 2012). "Furthermore, the study suggests that within vertical growth phase melanoma, although loss impacting on CDKN2A was most frequent, wider deletions involving P14ARF and even CDKN2B were associated with poorer histological prognostic factors." (PMID 20140953, 2010). "In Italy the likelihood to identify CDKN2A mutations in families with two melanoma cases was 25%." (PMID 24281082, 2010). "Its phenotypic and genotypic heterogeneity is extensive and requires careful scrutiny of its pattern of cancer associations, such as malignant melanoma associated with pancreatic cancer, in the familial atypical multiple mole melanoma syndrome, due to the CDKN2A germline mutation." (PMID 24281205, 2010). "CDKN2A was identified first as a tumor suppressor gene commonly deleted/mutated in tumor cell lines and subsequently its role as a high-risk susceptibility gene in melanoma families was elucidated." (PMID 20140953, 2010). "Also, notification of the presence of a family-specific mutation in the CDKN2A gene is an event that would be expected to increase the self-perception of melanoma risk." (PMID 20978504, 2010). "Loss of CDKN2A is a common occurrence even in early melanoma." (PMID 20140953, 2010). "A positive family history is a strongly associated risk factor for melanoma, and approximately 50% of affected families have mutations in one of the three following genes: cyclin-dependent kinase inhibitor 2A (CDKN2A), alternate reading frame (ARF), and cyclin-dependent kinase 4 (CDK4)." (PMID 21203498, 2010). "This is the first study to report on loss across the critical region of 9p in primary melanoma, although loss of CDKN2A coding for CDKN2A has been suggested by others to be associated with poorer prognosis and loss of CDKN2A expression immunohistochemically correlates with histological invasion." (PMID 20140953, 2010). "Moreover, the frequency of CDKN2A mutations is also higher in patients with synchronous or asynchronous multiple melanomas (more than two diagnosed lesions, 39.1%; only two melanomas, 10%)." (PMID 19828018, 2009). "The overall prevalence of melanoma patients who carry a CDKN2A mutation is between 0.2% and 2%." (PMID 19828018, 2009). "Although families identified with CDKN2A mutations display an average disease penetrance of 30% by 50 years of age and 67% by age 80, studies have shown that melanoma risk is greatly influenced by the year an individual is born, levels of sun exposure, and other modifier genes." (PMID 19828018, 2009). "However, the association between germline mutations in CDKN2A and malignancies other than melanoma are still unclear." (PMID 18628759, 2008). "Among the 214 melanoma-prone families recruited through the French Familial Melanoma Project, 46 families were positive for point mutations within CDKN2A (21.5%), one family carried a CDK4 point mutation in exon 2 (0.5%), and one family carried a large CDKN2A deletion (0.5%)." (PMID 18612309, 2008). "Finally, a splice site substitution mutation trimming CDKN2A exon 2 and severely affecting both p16INK4A and p14ARF was described in a family with melanomas, neurofibromas and multiple dysplastic nevi." (PMID 15928671, 2005). "Rare mutations in the CDKN2A gene are highly penetrant for melanoma." (PMID 12799637, 2003).